FANCG (FA complementation group G)
Diseases named in the same sentence as FANCG in open-access papers (continued):
Sharing a sentence is not in itself a finding about the gene and the disease.
tumor (13 papers, 2010 to 2025). "The downregulation of FANCG was associated with effective treatment with GEM and radiolabeled Trastuzumab in tumor xenograft model of disseminated intraperitoneal disease." (PMID 29871612, 2018). "In addition, the analysis of five available tumor samples from patients with FANCG GPVs revealed only one case of LOH at the FANCG locus." (PMID 39149814, 2024). "Additionally, there were high-confidence LoF variants at FANCG and CASP8 in two patients accompanied by somatic loss of heterozygosity in tumor, respectively." (PMID 34285288, 2021). "FANCG is a DNA repair gene which is a candidate tumor suppressor gene." (PMID 29876008, 2018). "Analyses of 18 surgical HCC specimens yielded no further examples for genetic or epigenetic inactivation of FANCC, FANCF, or FANCG in HCC, suggesting a low prevalence of proximal FA pathway inactivation in this tumor type." (PMID 20509860, 2010). "To further verify this hypothesis, we used lentivirus to overexpress FANCG gene in KYSE-30 cells, and then carried out the transplantation experiment in tumor-bearing nude mice again." (PMID 35364771, 2022). "Three patients had germline variants of uncertain significance (ACMG Class 3) in FANCG, RAD51B, and RPA1, respectively, whose allele frequencies were not increased in the tumor compared with the normal control sample." (PMID 30967556, 2019). "After overexpression of FANCG, the inhibition of xenograft tumor was significantly reduced in both the radiotherapy group and the combined group, and there was no statistical difference in tumor weight between the four groups (P > 0.05)." (PMID 35364771, 2022).
infection (1 paper, 2022). The state of being infected such as from the introduction of a foreign agent such as serum, vaccine, antigenic substance or organism. "Western blot and lentivirus infection model suggested overexpression of FANCG genes to confer radiosensitivity." (PMID 35364771, 2022).
FANCG also shares sentences with these, for which no sentence is quoted: lung carcinoma (2 papers); xeroderma pigmentosum (2); bone marrow failure (1); bowel cancer (1); brain tumors (1); breast tumors (1); chromosomal disorder (1); chromosomal instability syndrome (1); Cockayne syndrome (1); Cohen syndrome (1); congenital neutropenia (1); endometrial cancer (1); endometrioid ovarian carcinomas (1); Fanconi anemia complementation group A (1); Fanconi anemia complementation group G (1); Feingold syndrome (1); gastric tumor (1); Hepatitis B (1); leukemia (1); lymphoblastic lymphoma (1); lymphoma (1); myelodysplastic syndrome (1); myeloid leukemia (1); non-small cell lung carcinoma (1); osteoporosis (1); pancreatitis (1); pituitary stalk interruption syndrome (1); serous ovarian cancer (1); xeroderma pigmentosum group F (1).